FABP7 (fatty acid binding protein 7)
Diseases named in the same sentence as FABP7 in open-access papers (continued):
Sharing a sentence is not in itself a finding about the gene and the disease.
bipolar disorder (3 papers, 2014 to 2023). A disorder of the brain that causes unusual shifts in mood, energy, activity levels and the ability to carry out day-to-day tasks. "FABP-7 has been also investigated in relation to psychiatric diseases and it appeared that three single-nucleotide polymorphisms (SNPs) from FABP-7 showed nominal association with bipolar disorder." (PMID 36144237, 2022).
brain injury (3 papers, 2023 to 2025). Acute and chronic (see also brain INJURIES, CHRONIC) injuries to the brain, including the cerebral hemispheres, CEREBELLUM, and brain STEM. "Conversely, fatty acid-binding proteins (FABP1, FABP3, FABP4, FABP7) decreased over time in uninjured infants but increased in those with brain injury, suggesting a role in exacerbating damage." (PMID 40924950, 2025). "FABP7 knockdown increases permeability of the BBB, and exogenous administration of FABP7 following traumatic brain injury ameliorated BBB injury and restored impaired neurological function, suggesting that FABP7 is involved in the maintenance of barrier function." (PMID 37207357, 2023).
Cerebral ischemia (3 papers, 2021 to 2026). Restriction of arterial blood supply to the brain associated with insufficient oxygenation to support the metabolic requirements of the tissue. "Furthermore, Fabp7 is upregulated in response to early-life stress and cerebral ischemia, especially in hippocampal regions, suggesting an adaptive mechanism promoting synaptic remodeling, neurogenesis, and dendritic complexity." (PMID 41438503, 2026). "In summary, the present study suggested that increased FABP3, FABP5 and FABP7 expression in the brain is a novel biochemical marker of cerebral ischemia and that the FABP inhibitor, MF6 inhibited their expression levels to play a neuroprotective role in cerebral I/R in mice." (PMID 34068550, 2021).
clear cell renal cell carcinoma (3 papers, 2018 to 2022). "Higher FABP7 expression in clear cell renal cell carcinoma was shown to significantly correlate with distant metastasis and poor prognosis, suggesting that FABP7 could be a potential tumor marker and therapeutic target in patients with these tumors." (PMID 35783014, 2022). "In addition, higher expression of FABP7 was seen in clear cell renal cell carcinoma and the authors suggested that the gene activates the ERK and STAT3 signalling pathways." (PMID 30845926, 2019).
colorectal cancer (3 papers, 2020 to 2025). A primary or metastatic malignant neoplasm that affects the colon or rectum. "Colorectal cancer: High expression of FABP7 activates the MEK/ERK signaling pathway in colorectal cancer, inhibits cell apoptosis, and promotes cell cycle progression." (PMID 40717587, 2025). "In this study, we observed an upregulation of fatty acid-binding protein 7 (FABP7) in liver macrophages, which resulted in the accumulation of lipid droplets (LDs) within the PMN of colorectal cancer and pancreatic ductal adenocarcinoma." (PMID 40765822, 2025).
dementia (3 papers, 2022 to 2025). Loss of intellectual abilities interfering with an individual's social and occupational functions. "For example, the levels of FABP7 levels in the serum of patients with AD, PD, and other neurological disorders associated with dementia are considerably higher than those in non-dementia patients." (PMID 36077044, 2022).
depression (3 papers, 2014 to 2025). "Although a clear pattern of effects has been shown here for mechanisms implicated in depression and those involving FABP7, this study also has certain limitations." (PMID 40331773, 2025). "Western blotting, immunofluorescence staining, co‐immunoprecipitation, and Golgi‐Cox staining were employed to investigate the effect and mechanism of FABP7 in depression." (PMID 40331773, 2025). "In this study, a decrease in the protein expression of FABP7 in the CUMS depression model was observed." (PMID 40331773, 2025). "Here, we investigated the antidepressant properties of FABP7 using the chronic unpredictable mild stress (CUMS)‐induced model of depression and possible mechanisms." (PMID 40331773, 2025). "The expression of FABP7 in astrocytes is significantly reduced in depression models induced by acute reserpine administration and chronic corticosterone administration." (PMID 40331773, 2025). "Nonetheless, the impact of FABP7 on depressive disorders and the underlying mechanisms is not fully understood." (PMID 40331773, 2025). "However, the influence of FABP7 in depression triggered by stress, along with the related mechanisms, remains unclear." (PMID 40331773, 2025).
hyperlipidemia (3 papers, 2014 to 2023). "Of note, two patients, one of whom carried the FABP3 frameshift mutation (c.395delA) and one with the FABP7 frameshift mutation (c.239delA), suffered from hyperlipidemia." (PMID 25027319, 2014). "miR-21a-5p improved hyperlipidemia via the inhibition of its targets FABP7, 3-hydroxy-3-methylglutaryl CoA reductase (HMGCR), acetyl CoA acetyltransferase 1 (ACAT1), and oxidized low-density lipoprotein receptor 1 (OLR1)." (PMID 39872853, 2023). "And we think one of the mechanisms by which aerobic exercise improved hyperlipidemia was to up-regulate the expression of miR-21a-5p, thus inhibited the expression of target genes FABP7, HMGCR, ACAT1, and OLR1, which were closely related to lipid metabolism." (PMID 34099844, 2021). "Taken together, these results demonstrated that aerobic exercise improved hyperlipidemia through miR-21a-5p-induced inhibition of target genes FABP7, HMGCR, ACAT1, and OLR1." (PMID 34099844, 2021). "Our work identified miR-21a-5p as a potential regulator of aerobic exercise affecting lipid metabolism, achieved the favorable goal in hyperlipidemia by synergistically inhibiting the expression of target genes FABP7, HMGCR, ACAT1, and OLR1." (PMID 34099844, 2021).
liver steatosis (3 papers, 2014 to 2024). "Supplementation with 0.05% lycopene for 8 weeks inhibited liver steatosis in high-fat-fed mice through miRNA-21 induction, which then caused Fabp7 degradation and decreased fatty acid-binding protein 7 (FABP7) expression." (PMID 38645564, 2024). "An interesting report strengthens miR-21 association with steatosis showing that lycopene (an unsaturated carotenoid antioxidant) inhibits hepatic steatosis via miR-21-induced downregulation of its downstream target, the fatty acid-binding protein 7 (FABP7), in mice fed a high-fat diet." (PMID 24745023, 2014). "In addition, miR-21a-5p might also alleviate liver steatosis by directly suppressing hepatocyte Fabp7, one of its validated target genes." (PMID 39872853, 2023).
metastatic tumors (3 papers, 2021 to 2025). "FABP7+ macrophages transferred TG-enriched exosomes to CD8+ T cells, driving PD-1 upregulation, this interaction suggests therapeutic synergy between FABP7 inhibition and anti-PD1 immunotherapy in metastatic disease." (PMID 40765822, 2025).
neuroblastoma (3 papers, 2014 to 2018). Neuroblastoma (NB) is the most common solid, extracranial childhood tumor. "To test this hypothesis we performed transactivation experiments using a part of the Fabp7 promoter fused to luciferase (Fabp7::luc) as a reporter and transfected this construct into the neuroblastoma cell line NG108-15." (PMID 24932636, 2014).
prostate carcinoma (3 papers, 2006 to 2022). A carcinoma that arises from epithelial cells of the prostate gland. "FABP7 is expressed in many types of tumors, including brain, breast, colorectal, and prostate cancers, and is likely to play important roles in various cancers." (PMID 35783014, 2022). "Opposite results were reported in breast and prostate cancer, where decreased expression of FABP7 was found in tumor specimens when compared to normal tissues." (PMID 16623952, 2006). "Poorly-differentiated prostate tumors lose FABP7 expression, but more FABP7 is expressed in well-differentiated prostate cancer specimens than in primary normal prostate cells." (PMID 16623952, 2006).
steatosis (3 papers, 2014 to 2024). Increased lipid within the cytoplasm of cells. "Similar to this study we found the liver expression of FABP7 in rats to be significantly down-regulated during steatosis." (PMID 25470483, 2014). "Additionally, a comparison between drugs causing phospholipidosis and/or steatosis revealed 26 genes to be regulated in common including 4 signature genes to predict DIS (PKLR, GK, FABP7 and FADS1)." (PMID 25470483, 2014). "Furthermore, a comparison between drugs inducing phospholipidosis and/or steatosis uncovered 26 commonly regulated genes, including from the signature markers (PKLR, GK, FABP7 and FADS1)." (PMID 38791241, 2024).
adenoid cystic carcinoma (2 papers, 2022 to 2023). A malignant tumor arising from the epithelial cells. "In addition, the expression of both Notch1 and FABP7 had important prognostic value in patients who underwent resection of tracheobronchial adenoid cystic carcinomas." (PMID 35783014, 2022). "FABP7, as well as COL27A1, has been seen to be upregulated in head and neck adenoid cystic carcinoma." (PMID 37370820, 2023).
apocrine carcinoma (2 papers, 2014 to 2023). "The nuclear localization of FABP7 in tumor cells was shown to be associated with more aggressive stages of apocrine carcinomas." (PMID 25389781, 2014). "Expression of HMGCS2 and FABP7 is strongly associated with apocrine differentiation; their expression is retained by most invasive apocrine carcinomas (IAC) showing positive immunoreactivity in 100% and 78% of apocrine carcinomas, respectively, as compared to non-apocrine tumors (16.7% and 6.8%)." (PMID 25389781, 2014). "In total, FABP7 positives were detected in 14 out of the 205 breast non-apocrine carcinomas (6,79%): 8 out of the 42 TNBCs (19,04%); 1 out of the 103 Luminal A subtypes (0,97%); in none out of the 17 Luminal B (0%) and in 5 out of the 43 HER2+ (11,62%)." (PMID 25389781, 2014). "FABP7 also exhibited cytoplasmic intracellular localization in both apocrine carcinomas, however, in invasive stages, while retaining in cytoplasm, it was also detected in the nuclei with positivity thresholds more than 1%." (PMID 25389781, 2014). "However, apocrine carcinoma-associated genes such as ACSM1, FABP7, and HMGCS244 showed significant upregulation in TNAC compared to LK-TNBC (Wilcoxon signed-rank test, p < 0.05)." (PMID 37394589, 2023). "Expression of FABP7 and HMGCS2 by invasive apocrine cancer was further demonstrated by IHC using a well characterized set of apocrine carcinomas in which more than 90% of the tumor cells exhibited cytological features typical of apocrine cells." (PMID 25389781, 2014). "Here we report an analysis of the expression of two novel putative protein biomarkers, FABP7 and HMGCS2, in breast lesions undergoing apocrine differentiation: from benign apocrine metaplasia to invasive apocrine carcinoma." (PMID 25389781, 2014).
autism spectrum disorder (2 papers, 2014 to 2021). A spectrum of developmental disorders that includes autism, and Asperger syndrome. "FABP5 and FABP7 mRNA levels were higher in the cortexes of postmortem brains from schizophrenic patients than in those from healthy controls, and similar results were found for FABP7 mRNA in postmortem brains from patients with autism spectrum disorder." (PMID 34068550, 2021).
brain cancer (2 papers, 2024 to 2025). A primary or metastatic malignant neoplasm affecting the brain. "To understand the role of FABP7 and its modulated genes in tumor immunity, we investigated the association between their expression and the abundance of tumor-infiltrating immune cells (TIICs) in brain cancers, particularly LGG and GBM." (PMID 39596296, 2024). "Utilizing combined transcriptome profiling and pan-cancer analysis approaches, we report that FABP7 mediates the expression of multiple onco-immune drivers, collectively impacting tumor immunity and clinical outcomes across brain cancer subtypes." (PMID 39596296, 2024). "In this study, we performed a comprehensive analysis of large-scale transcriptomic datasets to investigate the oncogenic and immunomodulatory roles of FABP7 in brain cancers, focusing on LGG and GBM." (PMID 39596296, 2024). "In addition, specific FABP subtypes exhibit tissue- and context-dependent functions, with FABP4, FABP5, FABP6, and FABP7 being the most extensively studied in breast, liver, colorectal, and brain cancers." (PMID 40717587, 2025). "However, growing evidence from brain cancer model studies has suggested a novel nuclear role for FABP7." (PMID 39596296, 2024). "Despite these advances, it is largely unknown how FABP7 cooperates with other oncogenic drivers at the intracellular level to influence intercellular tumor immunity, particularly in the context of brain cancers." (PMID 39596296, 2024). "We also found that the expression of the onco-immune factors (ENO1, MUC1, COL5A1, IL11) that we identified was significantly correlated with FABP7 expression in patient brain cancers, particularly LGG, suggesting the pathological relevance of the results of our transcriptomic analyses." (PMID 39596296, 2024). "Notably, genes linked to brain cancer progression and tumor immunity (ENO1, MUC1, COL5A1, and IL11) were significantly downregulated (>2-fold) in KO brain tissue but were upregulated in FABP7 OV astrocytes." (PMID 39596296, 2024). "Overall, our findings suggest that FABP7 acts as an intracellular regulator of pro-tumor immunomodulatory genes, exerting a synergistic effect on the TIME and clinical outcomes in brain cancer subtypes." (PMID 39596296, 2024). "Collectively, these findings suggest that FABP7, in concert with the factors that it regulates, fosters a pro-tumor immunosuppressive TIME that influences tumor development and patient outcomes in different brain cancer subtypes." (PMID 39596296, 2024).
brain infarct (2 papers, 2021 to 2023). "In this study, we demonstrated that MF6 decreased brain infarction volumes and neurological deficits in mice subjected to tMCAO and reperfusion by inhibiting FABP3, FABP5 and FABP7 expression in the brain." (PMID 34068550, 2021).
colon cancer (2 papers, 2022 to 2025). "To assess the clinical relevance of FABP7, we performed survival analysis using colon cancer mRNA microarray data from the Kaplan-Meier Plotter database." (PMID 40765822, 2025).
epilepsy (2 papers, 2023 to 2025). A brain disorder characterized by episodes of abnormally increased neuronal discharge resulting in transient episodes of sensory or motor neurological dysfunction, or psychic dysfunction. "Comparing wake-dependent network activity relationships in electroencephalograph signatures between Fabp7 KO and WT mice before and after seizures merits future investigation and may support an epilepsy homeostasis hypothesis, wherein LoWS reduces aberrant brain activity." (PMID 40386682, 2025).
experimental autoimmune encephalomyelitis (2 papers, 2021 to 2023). An autoimmune demyelinating disease of the central nervous system that is produced experimentally in animals by the injection of homogenized brain or spinal cord in Freund's adjuvant. "FABP7 levels are upregulated in spinal cord astrocytes in a mouse model of experimental autoimmune encephalomyelitis and in primary cortical neuronal cultures after exposure to glutamate." (PMID 34068550, 2021).
Hepatic fibrosis (2 papers, 2025). The presence of excessive fibrous connective tissue in the liver. "We also demonstrated impaired phagocytic function of liver macrophages during acute liver injury and reduced levels of liver fibrosis induced by carbon tetrachloride (CCl4) in Fabp7-deficient mice compared to those in wild-type (WT) mice." (PMID 40017805, 2025). "In this study, we demonstrated that FABP7 in hepatic macrophages regulated M2 polarization and promoted liver fibrosis by activating fibroblasts and regulating CD4+ T-cell migration." (PMID 40017805, 2025). "Our study revealed that FABP7 in hepatic macrophages enhances liver fibrosis by regulating M2 polarization." (PMID 40017805, 2025). "Overall, this study showed that FABP7 in hepatic macrophages regulated PPARγ expression and M2 polarization, thereby promoting liver fibrosis via fibroblast activation and CD4+ T-cell migration." (PMID 40017805, 2025). "In summary, FABP7 in hepatic macrophages promotes liver fibrosis by regulating the migration of Th cells and the fibrotic response of HSCs via modulation of macrophage M2 polarization." (PMID 40017805, 2025). "To clarify the role of FABP7 in hepatic macrophages, we established two distinct models: one by inducing hepatic fibrosis via long-term administration of CCl4 and the other by inducing MASH using a high-fat high-cholesterol (HFHC) diet." (PMID 40017805, 2025). "Therefore, regulation of hepatic macrophage function by FABP7 is a potential therapeutic target for liver fibrosis." (PMID 40017805, 2025). "The diminished expression of TGF-β and CCL17 in Fabp7−/− macrophages may attenuate liver fibrosis by reducing myofibroblast activation and the migration of Th cells into the liver tissue." (PMID 40017805, 2025). "Therefore, in this study, we aimed to elucidate the mechanisms underlying the effects of FABP7 on the functions of hepatic macrophages in MASH and liver fibrosis models." (PMID 40017805, 2025). "Therefore, we aimed to elucidate the mechanisms underlying the effects of FABP7 on the functions of hepatic macrophages in metabolic dysfunction-associated steatohepatitis (MASH) and liver fibrosis models." (PMID 40017805, 2025). "In this study, we found that FABP7-deficient macrophages exhibited impaired M2 polarization, which reduced the fibrotic response of myofibroblasts and CD4+ T-cell infiltration into the liver tissues in a carbon tetrachloride (CCl4)-induced hepatic fibrosis model." (PMID 40017805, 2025). "Therefore, FABP7 in hepatic macrophages may be a potential therapeutic target for liver fibrosis." (PMID 40017805, 2025). "However, the precise mechanisms by which FABP7 regulates hepatic macrophage polarization in liver diseases, such as MASH and liver fibrosis, remain largely unknown." (PMID 40017805, 2025).
hepatocellular carcinoma (2 papers, 2021 to 2025). A malignant tumor that arises from hepatocytes. "Additionally, overexpression of miR-21-5p has been shown to inhibit lipid accumulation in H9C2 cells and significantly suppress stearic acid -induced intracellular lipid accumulation in mouse hepatocellular carcinoma cells by downregulating fatty acid binding protein-7 (FABP7) expression." (PMID 40045615, 2025).
ischemia (2 papers, 2021 to 2022). A hypoperfusion of the BLOOD through an organ or tissue caused by a PATHOLOGIC CONSTRICTION or obstruction of its BLOOD VESSELS, or an absence of BLOOD CIRCULATION. "Moreover, co-staining FABPs in different cell types in the cortical area of the penumbra suggests that increased FABP3, FABP5 and FABP7 expression occurred only in specific cells expressing these proteins before ischemia." (PMID 34068550, 2021). "However, it is unclear whether one FABP or FABP3, FABP5 and FABP7 collectively induced mPGES-1 after ischemia." (PMID 34068550, 2021). "However, it remains unclear whether the ischemia-induced enhancement of reactive astrocytes and FABP7 levels elicit beneficial or deleterious effects in neurons." (PMID 34068550, 2021). "However, despite the fact that FABP7 expression is upregulated in neuronal stem/progenitor cells after ischemia, transient ischemia that fails to result in hippocampal neuronal death does not appear to influence the process whereby FABP7 regulates neurogenesis." (PMID 36077044, 2022).
ischemic stroke (2 papers, 2022 to 2025). A stroke disorder caused by obstruction of blood flow to the brain, due to thrombotic (local blood clot formation) or embolic (due to a blood clot or other material traveling from another site) event. "Similarly, higher levels of serum FABP3 are observed in patients with ischemic stroke or myocardial infarction, and elevated levels of FABP7 are recorded in the serum of acute ischemic stroke patients." (PMID 36077044, 2022).